FBXO28 (F-box protein 28)
Diseases named in the same sentence as FBXO28 in open-access papers (continued):
Sharing a sentence is not in itself a finding about the gene and the disease.
tumor (9 papers, 2013 to 2024). "Flow cytometry and time-lapse microscopy analyses confirmed that depletion of FBXO28 resulted in a progressive loss of proliferation, evident from around 36–48 h of siRNA silencing in several different tumour cell lines." (PMID 23776131, 2013). "Here, we identify a hitherto uncharacterized F-box gene, FBXO28, encoding a cell cycle regulated protein with a critical function in tumour cell proliferation." (PMID 23776131, 2013). "Initially, FBXO28 was identified in a high-throughput, unbiased loss-of-function screen for genes required for efficient tumour cell proliferation." (PMID 23776131, 2013). "To evaluate the cancer-promoting activity of FBXO28 in vivo, we constructed a tumor xenotransplantation model in nude mice by subcutaneously injecting SKOV3 cells with FBXO28 knockdown or corresponding control cells." (PMID 38267923, 2024). "FBXO28 protein levels were positively associated with both PKAα and p-CREB levels, all of which were significantly higher in adjacent tissue than that in tumor counterparts." (PMID 37596321, 2023). "Tumor volume and weight were obviously higher in the FBXO28 overexpression group than in the control group, whereas they were markedly lower in the FBXO28 downregulation group." (PMID 37348029, 2023). "The E3 ligase F-box only protein 28 (FBXO28) belongs to the F-box family of proteins that play a critical role in tumor development." (PMID 37348029, 2023). "The data from GSE62165 showed that none of the six-FBXOs was associated with tumor location (N = 118), while GSE21501 displayed that FBXO28 and FBXO32 were tightly linked to tumor size (N = 98); FBXO32 was also related to lymphatic metastasis (N = 101)." (PMID 35046938, 2021). "In line with its role as a regulator of tumour cell proliferation, we discovered that cells depleted of FBXO28 downregulated genes activated by the transcription factor MYC." (PMID 23776131, 2013). "Since FBXO28 phosphorylation and overall expression levels are coupled to CDK activity, it is possible that the correlation between high FBXO28 levels and poor outcome partly reflects an increased proliferation in the tumours with high CDK activity." (PMID 23776131, 2013). "To further verify the role of the TGF-b1/Smad2/3 pathway in FBXO28 knockdown-mediated tumor inhibition, we performed rescue experiments in A2780 and SKOV3 cells with FBXO28 knockdown by transfecting a TGF-b1 overexpression plasmid to upregulate TGF-b1 expression." (PMID 38267923, 2024). "Interestingly, FBXO28 is found to exert either oncogenic or tumor suppressing functions by targeting MYC, SMARCC2 or HIF-1α, under different cellular contexts, complicating its role in tumorigenesis and metastasis." (PMID 37596321, 2023). "Downregulation of proteins mediating HIF-1α degradation, such as FBXO28, could provide these tumor cells with a further mechanism for this upregulation." (PMID 36115843, 2022). "IHC analysis of tumor tissue samples showed that FBXO28 upregulation enhanced the staining of the proliferation-associated genes Ki67 and proliferating cell nuclear antigen (PCNA), with a significantly higher proportion of positive cells in the FBXO28 upregulation group than in the control group." (PMID 37348029, 2023). "FBXO28 has been previously shown to regulate MYC activity in cancer cells, and was found in the same study to be upregulated on the mRNA level in various tumor entities." (PMID 36115843, 2022). "The function of FBXO28 in regulation of MYC activity is also supported by the findings that depletion or functional inactivation of FBXO28 attenuates MYC-induced transformation in vitro and MYC-driven tumour growth in vivo." (PMID 23776131, 2013). "Knockdown of FBXO28 also decreased the proliferation of normal human IMR90 cells and human diploid fibroblasts (HDFs), although to a lesser extent than the tumour cell lines." (PMID 23776131, 2013).
tumor (continued). "As for FBXO5, FBXO22, FBXO28, FBXO31 and FBXO45, they may be the independent poor prognostic factors of BC and the expression levels of which were closely related to different tumor stages." (PMID 33622332, 2021).
cancer (7 papers, 2013 to 2024). A tumor composed of atypical neoplastic, often pleomorphic cells that invade other tissues. "As enhanced invasiveness for metastasis is normally associated with tumorigenesis in cancer, we next investigated whether FBXO28 has a regulatory role in HCC proliferation under normal culture conditions." (PMID 37596321, 2023). "Supportively, a decreased expression of FBXO28 in mesenchymal cancer cell lines relative to epithelial counterparts was observed via transcriptome analysis of a large set of cancer cells." (PMID 37596321, 2023). "FBXO28 has been reported to participate in oncogenesis in a variety of human cancers." (PMID 38267923, 2024). "These experimental findings showed that FBXO28 is highly expressed in PC tissues and cell lines and is related to poor prognosis in patients with PC, indicating that FBXO28 may have a pro-cancer function in PC." (PMID 37348029, 2023). "High expression level of FBXO28 is associated with worse BC outcomes through non-proteolytic ubiquitination of MYC143 to stimulate cancer cell transcription." (PMID 33622332, 2021). "Together, these findings elucidate the novel function of FBXO28 as a critical inhibitor of EMT and metastasis in cancer and provide a mechanistic rationale for its candidacy as a new prognostic marker and/or therapeutic target in human aggressive HCC." (PMID 37596321, 2023). "Despite the implications of its role in cancer, the function of FBXO28 in epithelial-mesenchymal transition (EMT) process and metastasis for cancer remains largely unknown." (PMID 37596321, 2023).
FBXO28 also shares sentences with these, for which no sentence is quoted: Brain Abnormalities (1 paper); diabetes (1); Epileptic encephalopathy (1); glioma (1); gynecological tumours (1); liver cancer (1); lung carcinoma (1); neurological disorders (1); osteosarcoma (1); sarcoma (1).